CD14 (CD14 molecule)
Diseases named in the same sentence as CD14 in open-access papers (continued):
Sharing a sentence is not in itself a finding about the gene and the disease.
B cell lymphoma (10 papers, 2015 to 2023). "However, the underlying mechanism by which CD14+HLA-DRlow/− monocytes develop in patients with B-cell NHL is unknown." (PMID 26230952, 2015). "CD14+ primary monocytes were short-term stimulated with IFNγ to accomplish phagocytosis of 3D-cultured B-cell lymphoma cells (spheroids)." (PMID 38020313, 2023). "The present study extended this finding by showing that absolute numbers of CD14+HLA-DRlow/− monocytes are also increased in newly diagnosed B-cell NHL patients and that HLA-DR is downregulated across all three subsets of monocytes." (PMID 26230952, 2015). "The absolute numbers of CD14+ monocytes were higher in patients with B-cell NHL (707.7±155.4) than healthy donors (414.2±28.32, P=0.0119)." (PMID 26230952, 2015). "Next we determined the phenotype of CD14+HLA-DRlow/− monocytes from B-cell NHL patients by using 10-color flow cytometry." (PMID 26230952, 2015). "We have previously reported that monocytes from patients with B-cell NHL have an immunosuppressive CD14+HLA-DRlow/− phenotype that correlates with a poor prognosis." (PMID 26230952, 2015). "Taken together, these results suggest that elevated IL-10 serum levels contribute to increased numbers of immunosuppressive CD14+HLA-DRlow/− monocytes in B-cell NHL." (PMID 26230952, 2015). "In the present study, we show that IL-10 is critically involved in the development of the CD14+HLA-DRlow/− population in B-cell NHL." (PMID 26230952, 2015). "Supporting the role of IL-10 in facilitating CD14+HLA-DRlow/− cells in B-cell NHL, we observed that IL-10 pretreated monocytes exhibited suppressive properties by inhibiting activation and proliferation of T cells." (PMID 26230952, 2015). "Using peripheral blood samples from patients with B-cell NHL, we found that absolute numbers of CD14+ monocytic cells with an HLA-DRlow/− phenotype were higher than healthy controls and correlated with a higher International Prognostic Index score." (PMID 26230952, 2015). "In the present study, we measured the absolute counts of monocytes and CD14+HLA-DRlow/− cells in the peripheral blood of patients with B-cell NHL and assessed the effect of IL-10 on the development of CD14+HLA-DRlow/− monocytes." (PMID 26230952, 2015). "We identified IL-10 as being critically involved in the development of CD14+HLA-DRlow/− monocytes and find that IL-10 contributes to the expansion of this subset in B-cell NHL." (PMID 26230952, 2015). "In summary, we show that the absolute numbers of monocytes and percentage of CD14+HLA-DRlow/− monocytes are increased in newly diagnosed B-cell NHL patients." (PMID 26230952, 2015). "Taken together, these results reveal a novel role for IL-10 in inducing immunosuppressive CD14+HLA-DRlow/− monocytes in B-cell NHL that significantly suppress T-cell function." (PMID 26230952, 2015). "Given an extremely low frequency of CD14+ cells in biopsy specimens of B-cell NHL, we tested whether SIRPα was able to serve a marker for intratumoral Mo/MΦs." (PMID 31611550, 2019). "Furthermore, we evaluated the phenotype and function of CD14+HLA-DRlow/− cells, as well as biological and clinical relevance of these cells in patients with B-cell NHL." (PMID 26230952, 2015). "To identify which cytokine may be involved in the expansion of CD14+HLA-DRlow/− monocytes in B-cell NHL, we tested a panel of cytokines for their ability to decrease HLA-DR expression on CD14+ monocytes." (PMID 26230952, 2015). "To explore if monocytes mobilize and traffic into the center of spheroids, we labeled IFNγ-stimulated monocytes with PE anti-CD14 and co-cultured them with CFSE-labeled B-cell lymphoma spheroids." (PMID 38020313, 2023). "Positive expression of CD11a, CD79α, CD45, CD45RA, and MHCII and no expression of CD3, CD4, CD5, CD8, CD11d, CD14, CD21, CD34, and CD56 classifies it as a B-cell lymphoma." (PMID 27639374, 2016).
bladder cancer (10 papers, 2016 to 2026). "In contrast, the presence of HLA DR on CD14+CD16- monocytes and HLA DR on CD14+ monocytes are associated with an increased risk of bladder cancer." (PMID 39450166, 2024). "While CD14 is typically expressed in immune cells, a high level of CD14 expression has been observed in bladder cancer cells and is associated with the increased infiltration of myeloid cells, including neutrophils, compared with other cancer cells with minimal CD14 expression." (PMID 41486114, 2026). "In contrast, two immunophenotypes were identified as risk factors for bladder cancer: HLA DR on CD14+CD16- monocyte (OR: 1.10, 95% CI 1.03-1.18, p=0.0060) and HLA DR on CD14+ monocyte (OR: 1.11, 95% CI 1.03-1.19, p=0.0048) which are both Monocyte panel." (PMID 39450166, 2024). "The inflammatory factors generated by the high CD14 expression bladder cancer cells recruit and polarize macrophages and monocytes to acquire immune-suppressive characteristics." (PMID 37071001, 2023). "Bladder cancer cells with high CD14 can mediate tumor-promoting inflammation while driving cancer cell growth for promoting tumor development." (PMID 37071001, 2023). "The expression proportion of CD45+CD14+CD163+ mono-macrophage subset in bladder cancer tissue (n = 8) was significantly higher than that in adjacent normal tissues (n = 3, 67.88 ± 7.2% vs. 27.05 ± 11.18%, P = 0.001)." (PMID 34803459, 2021). "It is prompted that CD45+CD14+CD163+ mono-macrophage subset is significantly increased in bladder cancer microenvironment, which is one of the characteristics of tumor immune microenvironment." (PMID 34803459, 2021). "Recently, CD14 expression in bladder cancer cells was identified as a mechanism of tumor progression." (PMID 29777108, 2018). "Moreover, immunofluorescence performed on bladder cancer tissue samples revealed that samples with high IGF2BP2 expression exhibited relatively high levels of CD14 and CD68, consistent with the TCGA‐BLCA and spatial transcriptomics findings." (PMID 39711402, 2024). "CD14 is a key molecule in innate immunity activation, patients with bladder cancer with high CD14 levels may develop a proliferative tumor microenvironment." (PMID 36425064, 2022). "In the bladder cancer patient urine analysed here, CD15+CD14+ cells also expressed CD16, CD11c and HLA-DR." (PMID 36189320, 2022). "In bladder cancer tissue, the expression rate of CD40 in CD45+CD14+CD163- mono-macrophage subset was significantly lower than that in CD45+CD14+CD163+ mono-macrophage subset." (PMID 34803459, 2021). "Bladder cancer (BC) patients had significantly higher ratios of both TREM-1%/TREM-2% (p < 0.001) and mean fluorescence intensity (MFI) TREM-1 MFI/TREM-2 MFI (p = 0.004) expressions on CD14+ monocytes compared to healthy subjects, TREM-2 MFI being significantly lower (p = 0.025)." (PMID 39684475, 2024).
breast tumor (10 papers, 2013 to 2023). "We aligned CD1c+CD14+ cells infiltrating breast tumor-draining lymph node with blood DC3s compared to cDC2s and monocytes." (PMID 32610077, 2020). "CD1a+, CD1a+CD14+, and CD14+ DDC are subsets that range from more to less mature respectively; we found a clear shift to a predominance of immature CD14+ subsets among DC migrated from breast tumor-overlying skin." (PMID 23875023, 2013). "Triple-negative subtype of breast tumors expressed higher levels of MCP1 and CD14 than those of luminal subtype breast tumors and bone metastatic status exhibited higher MCP1 and CD14 levels compared to brain metastatic status." (PMID 31935914, 2020). "The effects of 1,25(OH)2D3 0.5nM on the expression of CYP24A1, DPP4, IL1RL1, CD14, CA2 and BMP6, were further explored in breast tumor derived cells, representing the epithelial and stromal compartments, using RT-qPCR." (PMID 23497279, 2013). "However, using scRNASeq data from breast tumors, we mainly observed an expression of CMKLR1 in a subset of TAM C1QC+ that expressed usual M2 signature, including high expression of CD14 and CD163, whereas CMKLR1 expression was low in a subset of TAM ISG15+ that expressed classical M1 signature." (PMID 37539056, 2023). "In our analysis of the TCGA breast tumor cohort, we observed significant positive correlations between TREM1 expression and the expression of TREM-1 target cytokines (IL1B, IL8, IL6 and CCL2) and markers of MDSCs and TAMs (CD11B/ITGAM, OLR1, CD14 and CD206/MRC1)." (PMID 34956864, 2021).
chronic lymphocytic leukemia (10 papers, 2013 to 2025). "Studies have also indicated that soluble CD14 secreted by monocytes supports the survival of chronic lymphocytic leukemia cells." (PMID 39744475, 2025). "CD14+HLA-DRlow MDSCs accumulate in patients with B cell-derived chronic lymphocytic leukemia (CLL) and induce immune defects that prevent an efficient anti-tumor response." (PMID 31438991, 2019). "In chronic lymphocytic leukemia (CLL), CD14-positive cells that express CSF1R support CCL cell survival, and treatment with GW2580 or ARRY-382 decreases CCL cell viability." (PMID 32801364, 2020).
Cognitive impairment (10 papers, 2013 to 2025). Abnormal cognition is characterized by deficits in thinking, reasoning, or remembering. "HCV/HIV coinfection was associated with a type I IFN CD14+ monocytes activation profile and correlated with cognitive impairment." (PMID 31447817, 2019). "A very recent set of studies suggests a mechanism for CCR2/CCL2 signaling in the recruitment and trafficking of CD14 + CD16+ monocytes into the brain in HIV-associated cognitive impairment." (PMID 25852823, 2015). "The CD14 + CD16+ monocytes that crossed an artificial blood–brain-barrier model as well as those found in the CSF of individuals with HIV-associated cognitive impairment, were found to preferentially express CCR2." (PMID 25852823, 2015). "However, we found significant elevations in levels of EVs expressing monocyte-associated markers in HIV+ persons with cognitive impairment including CD14+EVs, CD16+EVs, CD192+EVs, CD195+EVs, as well as EVs expressing glial fibrillary acidic protein (GFAP)." (PMID 36601110, 2022). "This CD14+ HIV DNA reservoir is proportionally small compared to that found in CD4+ T-lymphocytes; however, the overall CD14+ reservoir size has been linked to cognitive disorders among both cART-treated and untreated patients in past cross-sectional post-hoc correlative studies." (PMID 23936155, 2013). "Regarding CD14, it is an inflammatory marker positively related to brain atrophy, cognitive impairment, and incident dementia." (PMID 35356296, 2022). "Increased circulation of intermediate monocytes (CD14+CD16+) infected with HIV is associated with immune activation and cognitive impairment in cross-sectional studies." (PMID 33914710, 2021). "The objective of this study was to determine if the level of HIV DNA in CD14+ enriched monocytes predicted cognitive impairment and brain injury." (PMID 23936155, 2013). "CD14+CD16+ monocyte transmigration across the blood brain barrier is associated with cognitive impairment in people with HIV who are virally suppressed and without significant confounders." (PMID 39253970, 2024). "Additionally, increases in peripheral soluble CD14 and CD163 remain markers commonly associated with CNS injury, specifically with cognitive impairment." (PMID 33914710, 2021). "Thus, even in the context of viral suppression, CD14+CD16+ monocyte entry into the CNS may be a mechanism that contributes to cognitive impairment." (PMID 39253970, 2024). "Plasma-EVs expressing CD14, CD16, CD192, C195, and GFAP were significantly higher in HIV-infected individuals with cognitive impairment compared to individuals with normal cognition." (PMID 36601110, 2022). "Furthermore, we also found that plasma-EVs expressing monocyte-associate markers, including CD14, CD16, CD192, and CD195 were significantly elevated in HIV-infected individuals with cognitive impairment compared to those without cognitive impairment." (PMID 36601110, 2022).
coronary atherosclerosis (10 papers, 2013 to 2025). Atherosclerosis of the coronary vasculature. "The increased level of Lp(a) and the decreased quantity of classical CD14++CD16− monocytes were associated with the severity of coronary atherosclerosis." (PMID 34206012, 2021). "CD14 + CD16 + monocyte increased number was associated with diagnosis of coronary atherosclerosis." (PMID 35900662, 2022). "The TT genotype is found in 17% of healthy controls, but only in 5% of patients with coronary atherosclerosis—3% for Group A and 7% for Group B. CD14 C260T promoter polymorphism could be implicated in protective pathways against CAD." (PMID 29367560, 2016). "It was found that the increase of CD14 + monocytes in coronary atherosclerosis patients was significantly correlated with the severity." (PMID 35773742, 2022). "In the current study, we used integrated WGCNA methods to analyze the dataset and identify two hub genes (TLR2 and CD14) that were positively correlated with the severity of coronary atherosclerosis." (PMID 33574831, 2020). "In our current research, we also found that CD14 is related to the severity of coronary atherosclerosis and the vulnerability of plaques." (PMID 33574831, 2020). "In patients with coronary atherosclerosis, deletion of RFX1 activates TLR4 and is involved in disease progression through histone modifications that further activate CD14+ monocytes." (PMID 41425715, 2025). "Gating strategy based on CD14 and CD16 is the most popular classification method for the monocyte subsets among studies on coronary atherosclerosis." (PMID 32922178, 2020). "Restoring HDL-C functionality might be a way to modulating CD14 and CD16 expression, which may be a potential mechanism to reverse the abnormal monocyte phenotype and prevent coronary atherosclerosis." (PMID 32922178, 2020). "Thus far, the influence of lipids on the expression of CD14 and CD16 on monocyte subsets in coronary atherosclerosis (CA) remains unclear." (PMID 32922178, 2020). "We conclude that the frequency of non-classical CD14+CD16hi monocytes in patients with stable IHD is indirectly related to the severity of coronary atherosclerosis, whereas classical CD14++CD16lo monocytes are directly associated with the Gensini score and inflammatory biomarkers." (PMID 33854919, 2020). "Therefore, the aim of this study was to explore whether blood lipids are related to the expression of CD14 and CD16 on monocyte subsets, which may in turn lead to the changes in the proportion of monocyte subsets in coronary atherosclerosis patients." (PMID 32922178, 2020).
liver cancer (10 papers, 2017 to 2025). An epithelial or non-epithelial malignant neoplasm that arises from the liver. "Concentrations of anti-flagellin IgA (1.13, 1.01-1.28) and IgG (1.13, 1.01-1.28), anti-lipopolysaccharide IgG (1.20, 1.01-1.42), and soluble CD14 (1.12, 1.01-1.24) were also associated with liver cancer risk." (PMID 41129365, 2025). "To investigate the expression of G0S2 in liver cancer tissues, we performed mIHC using antibodies against CD14, CD68, and G0S2 on an HCC tissue microarray to enable double staining with the monocyte markers." (PMID 40282408, 2025). "In patients with liver cancer, depletion of CD14+HLA-DR−/low M-MDSCs enhances IFN-γ secreting CD4+ T cells specific to α-fetoprotein." (PMID 32793192, 2020). "The proportion of cells expressing CD14 was lower in liver cancer cells cultured in MRC-5-CM than in liver cancer cells cultured in normal medium." (PMID 31523179, 2019). "The proportion of CD14+ cells was seemingly lower in liver cancer cells cultured in MRC-5-CM than in liver cancer cells cultured in normal medium." (PMID 31523179, 2019). "In liver cancer patients, the CD14+HLA-DR–/low MDSCs were significantly increased and the MDSCs exert their immunosuppressive function through the induction of Treg." (PMID 28178645, 2017). "TGR5 receptors have many different agonists, but DCA and LCA are effective components that are able to inhibit tumor necrosis factor-α production in CD14+ macrophages by increasing the cAMP content to regulate NF-κB-p65 activation in the macrophages of liver cancer cells." (PMID 34885648, 2021). "We found that CD14, CD25, and CD28 can also be expressed by liver cancer cells, but their roles need to be further explored." (PMID 31523179, 2019). "Thus, we evaluated the influence of MRC-5-CM on expression of TLRs and leukocyte-differentiation antigens (CD14, CD25, CD28, and CD61) in liver cancer cells." (PMID 31523179, 2019). "On the contrary, CD14+HLA-DR−/low MDSCs from patients with liver cancer show no TGF-β secretion." (PMID 32793192, 2020).
stable angina (10 papers, 2012 to 2025). "CD14++ monocytes were isolated from 14 long COVID patients with cardiovascular symptoms (e.g., dyspnea, angina) and 10 age-matched controls with similar cardiovascular risk profiles." (PMID 40429707, 2025). "A research detected that patients with stable angina pectoris displayed significantly elevated CD14 + CD16 + CX3CR1 + monocyte counts compared with patients without vulnerable plaques." (PMID 39820843, 2025). "Human studies showed that CD14+ monocyte TLR4 expression is increased in unstable angina and acute MI compared to control and stable angina groups." (PMID 27795867, 2016). "(B) Circulating levels of CD14+HLA-DRneg/low monocytes in patients with unstable angina (UA; n=11), non-ST-elevation MI (NSTEMI, n=16), and ST-elevation MI (STEMI, n=44)." (PMID 34289931, 2021).
allergic asthma (9 papers, 2012 to 2023). A asthma with a basis in a pathological type I hypersensitivity reaction. "This study also demonstrates that the CD14 (−159 C/T) polymorphism is a risk factor for moderate-severe allergic asthma in adult Caucasians." (PMID 29515128, 2018). "Several epidemiological analyses have highlighted positive associations between TLR2, TLR4 and CD14 (TLR4s co-receptor) gene polymorphisms and allergic asthma susceptibility in human." (PMID 24098413, 2013). "Indeed, we evidence an association of the T allele and TT genotype of CD14 (−159 C/T) polymorphism with reduced risk of moderate-severe allergic asthma." (PMID 29515128, 2018). "Moreover, we noticed an association of the T allele (P = 0.0162) and TT genotype (P = 0.0196) of the CD14 SNP with a decreased risk of allergic asthma and augmented sCD14 levels." (PMID 29515128, 2018). "Moreover, we evidence an association of the (−159 C/T) SNP in the CD14 promoter with allergic asthma, and a decreased risk of having moderate-severe allergic asthma in carriers of T allele and TT genotype." (PMID 29515128, 2018). "Recently, it was reported that subjects with allergic asthma have increased expression of CD14 after LPS inhalation." (PMID 24891765, 2014). "Therefore, it seems necessary to undertake new works aimed to the simultaneous measurement of both membrane and soluble forms of CD14 as well as the CD14 (−159 C/T) SNP in adult Caucasian subjects with allergic asthma and different degrees of severity (intermittent-mild and moderate-severe)." (PMID 29515128, 2018). "In line with the in vivo data, in vitro stimulation of human PBMCs of allergic patients with holo-, but not apo-BLG, lowered the relative numbers of CD14+ monocytes/macrophages, important contributors to the pathogenesis of allergic asthma." (PMID 33746954, 2021). "Interestingly, IgE+CD14+ cells were present at higher frequencies in BAL cells from horses with mEA compared to sEA horses, hinting towards different endotypes of allergic or non-allergic asthma pathogenesis dominating those two phenotypes of EA." (PMID 35874777, 2022).